IFI16 (interferon gamma inducible protein 16)
Diseases named in the same sentence as IFI16 in open-access papers (continued):
Sharing a sentence is not in itself a finding about the gene and the disease.
HCMV infection (20 papers, 2012 to 2025). "At both high and low MOI HCMV infection, WT and K90R IFI16 restricted virus replication, whereas K90Q caused a nearly complete loss of function." (PMID 39772686, 2025). "Recent studies, however, showed that IFI16 shuttles between the nucleus and the cytoplasm upon the cytomegalovirus infection, possibly relocating IFI16 to the site of the DB DNA sensing." (PMID 36552792, 2022). "Given that enhanced GLUT4 expression results in increased glucose uptake, we sought to assess glucose consumption in IFI16 KO versus WT HFFs following HCMV infection." (PMID 35420480, 2022). "Since live-cell studies revealed a re-localization of IFI16 to nuclear peripheral foci within the first hours of HCMV infection, it can be assumed that IFI16 rapidly targets incoming HCMV DNA." (PMID 33530304, 2021). "During HCMV infection, the viral dsDNA genome is recognized by IFI16 resulting in a colocalization inside the cell nucleus." (PMID 33530304, 2021). "Accordingly, siRNA-mediated silencing of IFI16 dampens cytokine transcription in response to HCMV infection." (PMID 32117146, 2020). "Upon HCMV infection, IFI16 is activated in the nucleus and undergoes oligomerisation, which is a prerequisite for it to promote the immune response." (PMID 32117146, 2020). "During nuclear DNA sensing in response to HSV-1 and HCMV infections, IFI16 oligomerization was shown to undergo distinct temporal phases, which likely represent different steps of the antiviral response." (PMID 31337724, 2019). "In particular, IFI16 can act as a viral restriction factor during human cytomegalovirus (HCMV) infection by interfering with Sp1-mediated transcriptional activation of viral genes." (PMID 31861809, 2019). "On the other hand, studies have also shown that IFI16 is dispensable for the IFN response to HCMV Infection in knock out cell models." (PMID 28529930, 2017). "DNA sensors such as DNA-dependent activator of IFN-regulatory factors (DAI), IFI16 or cGAS were reported to detect HCMV infection to induce type I IFN activation." (PMID 29018427, 2017). "In contrast, when IFI16 was overexpressed prior to HCMV infection, luciferase activity decreased by more than 75% or 90% in cells transfected with the pUL54 0.4 or pUL54 0.3 indicator plasmids respectively, compared to AdV LacZ control cells." (PMID 22291595, 2012). "During HCMV infection, IFI16 is increasingly lactylated at multiple sites in its IDR region." (PMID 39772686, 2025). "This may contribute to the observed mislocalization of IFI16 to the cytoplasm late during HCMV infection." (PMID 39772686, 2025). "In particular, at the late stage of cytomegalovirus (HCMV) infection, IFI16 binds to the viral structural protein, PUL97, and is phosphorylated and mislocalized to the cytoplasmic virus assembly complex, which allows HCMV to escape the intracellular viral restriction." (PMID 37410794, 2023). "As ChREBP translocation to the nucleus induces lipogenic enzyme transcription, and HCMV infection increases de novo fatty acid synthesis through transactivation of lipogenic enzymes, we asked whether IFI16 would also play an inhibitory role in these processes." (PMID 35420480, 2022). "Furthermore, during human cytomegalovirus (HCMV) infection, IFI16 translocated into the cytoplasm during early stage and improved vesicle sorting and binding ability." (PMID 35459254, 2022). "Moreover, reciprocal IPs corroborate these results, establishing that IFI16 selectively interacts with ChREBP during HCMV infection." (PMID 35420480, 2022). "To determine whether SOAT1 gene expression was affected by HCMV replication and/or IFI16 sensor activity, we examined its mRNA expression pattern during a time course of HCMV infection of WT and IFI16 KO HFFs." (PMID 35420480, 2022). "Thus, the interaction with pp65 appears critical for the outcome of HCMV infection as it modulates the intrinsic and innate immune activities of IFI16." (PMID 33530304, 2021).
HCMV infection (continued). "However, UL83 prevents IFI16 oligomerisation, thus disarming the antiviral effect of IFI16 during HCMV infection." (PMID 32117146, 2020). "During early stages of HSV-1 and HCMV infections, the Everett group and our group observed rapid IFI16 puncta formation at sites of nuclear viral genome deposition, and we further demonstrated that the IFI16 PYD was sufficient for this dynamic relocalization." (PMID 31337724, 2019). "Therefore, to provide new evidence about the action of IFI16 in the context of HCMV infection, promoter scan analyses, EMSA and ChIP, were each performed in IFI16-overexpressing HELFs infected with HCMV." (PMID 22291595, 2012). "Finally, lipids containing medium-chain fatty acid substituents with up to 2 double bonds (e.g., PC32:0, PC32:1, and PC34:0), lysoglycerophosphocholines (lysoPCs), and some diacylglycerolphosphoserines (PSs) were significantly downregulated in IFI16 KO versus WT HFFs following HCMV infection." (PMID 35420480, 2022). "Thus, IFI16 appears to downregulate ChREBP activity during HCMV infection." (PMID 35420480, 2022). "Human cytomegalovirus (HCMV) infection on human embryonic lung fibroblasts induced viral pUL97-mediated phosphorylation on IFNγ-inducible protein 16 (IFI16), which facilitates the mis-localization of IFI16 into the cytosol to disable its viral DNA sensing ability." (PMID 35795661, 2022). "Similarly, IFI16 has been reported to be dispensable for IFN production in mice following HCMV infection and this apparent independence may also stem from the reported ability of HCMV to interfere with IFI16 signaling." (PMID 33042875, 2020). "We previously observed that IFI16 undergoes dynamic changes in its subnuclear localization at the early stages (30 min–2 h) of HSV-1 and HCMV infections." (PMID 37283074, 2023). "Here, we unveil an unprecedented selective interaction between IFI16 and ChREBP to modulate GLUT4 expression during HCMV infection, resulting in decreased glycolytic and lipogenic gene expression." (PMID 35420480, 2022). "While IFI16 induces cytokines, only cGAS activates STING/TBK-1/IRF3 and apoptotic responses upon HSV-1 and HCMV infections." (PMID 27935834, 2016). "In contrast, after 24 h of HCMV infection, we recorded a 6-fold induction of ChREBPα expression in cells lacking IFI16, which was almost three times as high as that seen in WT cells that were similarly infected." (PMID 35420480, 2022). "As IFI16 mediates intrinsic resistance to HCMV, we asked whether it might counteract the metabolic rewiring promoted by HCMV infection." (PMID 35420480, 2022). "For instance, it was found that IFI16 is not required for cGAS/STING/TBK-1 signaling in HFFs following HSV-1 or HCMV infection, but was for the transcription of IFN-β, ISG54, ISG56, and RANTES." (PMID 33042875, 2020). "Upon HCMV infection, the protein levels of the CDS interferon gamma inducible protein 16 (IFI16), as well as of the transcription factors IRF3 and NF-κB are steadily downregulated, indicating that viral proteins target these important determinants of CMV infection." (PMID 28542326, 2017). "IFI16 undergoes multiphasic subnuclear dynamics during HSV-1 and HCMV infections." (PMID 27935834, 2016). "However, as with infection of MyD88-expressing cells, we observed that the UL88-STOP-mCh HCMV infection, in which MyD88 levels are higher, actually downregulated a number of antiviral ISGs, including IFITM1, IFITM2, IFITM3, MX1, and IFI16 (the nuclear sensor that plays a role in sensing of HCMV)." (PMID 40638072, 2025). "Thus, we asked whether IFI16 could also act as an RF against HCMV within the metabolic compartment, which is essential to achieve a productive HCMV infection." (PMID 35420480, 2022). "Since pUL83 is the most abundant tegument protein of HCMV with more than 2000 molecules being integrated into the mature virion, inhibition of IFI16 may occur right after HCMV infection without the need of viral gene expression." (PMID 27058035, 2016).
HCMV infection (continued). "IFI16 overexpression before HCMV infection did not further reduce the HCMV-driven transactivation of the IR-1 mutant construct in terms of luciferase activity, indicating that the DNA target of IFI16 suppressor activity might reside in the IR-1 element." (PMID 22291595, 2012). "Although IFI16 knockdown (KD) enhances HCMV replication, a recent study indicates that cGAS, but not IFI16, is required for the STING signaling pathway in human fibroblast upon HCMV infection." (PMID 29018427, 2017).
systemic lupus erythematosus (19 papers, 2011 to 2024). An autoimmune multi-organ disease typically associated with vasculopathy and autoantibody production. "For example, aberrant expression of the nuclear DNA sensor IFI16 has been associated with several autoimmune diseases, including Sjögren's syndrome, systemic lupus erythematosus, systemic sclerosis, inflammatory bowel disease, rheumatoid arthritis, and psoriasis." (PMID 37283074, 2023). "For example, aberrant expression of IFI16 has been linked to several autoimmune diseases, including systemic lupus erythematosus (SLE) and Sjögren’s syndrome." (PMID 35575489, 2022). "Recent studies have reported anti-IFI16 antibodies in the sera of patients with autoimmune diseases such as systemic lupus erythematosus, inflammatory bowel diseases, and rheumatoid arthritis." (PMID 37998338, 2023). "These proteins form large, shield-like structures around strands of DNA, and previous work has shown that some people with lupus make antibodies against IFI16." (PMID 35608258, 2022). "Inhibition of AIM2 promoted the expression of another IFI member IFI16/p202, which was found increased in leukocytes of lesion skin and peripheral blood from lupus patients." (PMID 31427885, 2019). "Another autoantigen suggested to be involved in lupus is interferon-inducible protein 16 (IFI16), a DNA binding protein with diverse roles that is normally localized to the nucleus." (PMID 30405625, 2018). "Evidence supports a role of AIM2, IFI16, and the regulatory p202 proteins (p202a and p202b) in the pathogenesis of Sjogren’s syndrome and systemic lupus erythematosus (SLE)." (PMID 24367371, 2013). "Moreover, AIM2 and IFI16 filaments also persist and are even stigmatized as autoantigens in debilitating autoimmune disorders such as systemic lupus erythematosus and Sjögren’s syndrome." (PMID 38252125, 2024). "Renal IFI16 expression was positively associated with systemic lupus erythematosus disease activity index (SLEDAI) and serum creatinine while negatively related to baseline eGFR and serum complement C3." (PMID 37393341, 2023). "In addition, overexpression of IFI16 leads to autoimmune diseases such as systemic lupus erythematosus (SLE) and Sjogren Syndrome (SjS) in which DNA is a major autoimmune target." (PMID 35459254, 2022). "For example, patients with systemic lupus erythematosus, Sjögren Syndrome, and systemic sclerosis exhibit significantly elevated levels of anti-IFI16 antibodies, which can result from aberrant overexpression and mislocalization of IFI16." (PMID 33255247, 2020). "Summary of IFN-inducible protein 16 (IFI16) correlations with systemic lupus erythematosus (SLE) and other autoimmune diseases." (PMID 29892303, 2018). "In recent years, two ALR family members, the interferon (IFN)-inducible protein 16 (IFI16) and AIM2, have been linked to the pathogenesis of various autoimmune diseases, among which systemic lupus erythematosus (SLE) has recently gained increasing attention." (PMID 29892303, 2018). "Considering the antagonizing relationship of IFI16 and AIM2, how AIM2 and IFI16 work in lupus is worthy of further investigation." (PMID 31427885, 2019). "Moreover, the critical cytokine of lupus, IFN-α, can influence expression/activity of both AIM2 and IFI16." (PMID 31427885, 2019). "In addition, elevation of IFI16 in patients with autism compared to control subjects could also ascertain the role of autoimmunity in the pathophysiology of autism as, interestingly, anti-IFI16 antibodies are present in autoimmune diseases such as systemic lupus erythematosus." (PMID 24400970, 2014).
melanoma (18 papers, 2018 to 2025). A malignant, usually aggressive tumor composed of atypical, neoplastic melanocytes. "Survival analysis recognized that only IFI16 displayed good prognostic significance in patients with primary melanoma among the 14 validated feature genes." (PMID 34930258, 2021). "The Socransky trait was associated with SNPs that interfered with genes encoding interferon gamma inducible protein 16 (IFI16) and absent in melanoma 2 (AIM2), proteins that form inflammasomes, and lead to increased levels of mature IL‐1β upon a microbial challenge." (PMID 32533779, 2020). "PRMT5 methylates IFN-γ inducible protein 16 (IFI16) and suppresses NLRC5 transcription, inhibiting the cGAS-STING and MHCI pathways in melanoma, thereby weakening IFN signaling and antitumor immune responses." (PMID 40166469, 2025). "PRMT5 methylates IFI16/IFI204 and inhibits NLRC5 transcription, suppresses inflammation and antigen presentation, and promotes melanoma growth." (PMID 37163421, 2023). "The expression levels of nucleic acid sensors interferon gamma-inducible protein 16 (IFI16) and absent in melanoma 2 (AIM2) in peripheral blood mononuclear cell (PBMC) and skin from AOSD patients and HCs were analyzed by PCR and immunohistochemistry." (PMID 31068953, 2019). "Moreover, extracellular IFI16 promotes TLR4‐mediated inflammation via LPS binding, sustains STING expression to activate IFN‐γ signaling in melanoma, and exerts antitumor effects by inducing apoptosis, inhibiting neovascularization, and enhancing macrophage recruitment." (PMID 41316520, 2025). "Furthermore, upregulation of IFI16, IFI204, and NLRC5 could limit melanoma growth in mice and improve the survival of patients with melanoma." (PMID 37163421, 2023). "AIM2 (absent in Melanoma 2) and IFI16 (Interferon Gamma Inducible Protein 16) belong to the PYHIN family (PYD-like and HIN domain-containing proteins)." (PMID 37577033, 2023).
herpesvirus infection (17 papers, 2013 to 2025). "Other studies have demonstrated involvement of the IFI16 inflammasome in herpesviridae infections, such as infections of Kaposi's sarcoma-associated herpesvirus (KSHV) and herpes simplex virus (HSV)-1." (PMID 28369146, 2017). "For example, IFI16 can induce the inflammasome in response to Kaposi’s sarcoma-associated herpesvirus infection and act as a mediator of the anti-inflammatory actions of type I IFNs." (PMID 24138989, 2013). "Nuclear activation of interferon gamma-inducible protein 16 (IFI16) inflammasome could be detected during Kaposi sarcoma-associated herpesvirus infection in endothelial cells." (PMID 33328988, 2020). "Functional analyses demonstrate that IFI16 K90 lactylation, a modification conserved across both herpesvirus infections, is proviral for these viruses through inhibition of IFI16 functions in viral gene suppression and cytokine signaling." (PMID 39772686, 2025). "Other studies revealed that both cGAS and IFI16 are required for the IFN responses to herpesvirus infections." (PMID 35458396, 2022). "The details of the mechanism of IFI16 trafficking to STING is not well understood; however, a partial insight into IFI16 trafficking was gained during a study of IFI16 signaling in the nucleus during herpesvirus infection." (PMID 35458396, 2022). "While it is clear that IFI16 plays a key role in the induction of ISG expression during herpesvirus infection, we have also identified an important and novel role for PML in this host response to HSV-1 infection." (PMID 29309427, 2018). "None of the differentially regulated genes were linked to antiviral immunity associated with herpesvirus infections (for example, MX2, IFI16, CGAS, IFITs and OASs32,82–84), indicating that the anti-VZV function of NPHP4 is probably independent of the innate immune defence." (PMID 40739040, 2025). "Additionally, the dichotomy of IFI16 action in antiviral defense at two distinct subcellular locations against herpesvirus infection requires further investigation." (PMID 31798565, 2019). "For instance, the dsDNA sensor IFI16, which activates IFN-β responses and forms an inflammasome, is degraded in HSV-1 infected cells by ICP0 proteasomal targeting and in cells with lytic Kaposi's Sarcoma-Associated Herpesvirus infection." (PMID 31867020, 2019). "IFI16 was shown to bind viral DNA and to induce antiviral cytokines, and our findings indicate a likely viral DNA sensing event at the nuclear periphery early in herpesvirus infection." (PMID 27935834, 2016). "The localization of IFI16 to nuclear peripheral foci upon herpesvirus infections and its well-characterized binding to viral DNA suggest that these foci may be sites of viral DNA deposition." (PMID 27935834, 2016). "In summary, our studies demonstrate that the post-genome recognition event of IFI16’s acetylation by histone acetyltransferase p300 is required for the IFI16-mediated innate immune responses of inflammasome induction, IL-1β and interferon-β production during herpesvirus infections." (PMID 26134128, 2015). "Thus, the temporal kinetics of IFI16 recruitment to vDNA and its subsequent association with PML-NB host factors has remained poorly defined, specifically under MOI conditions relevant to WT herpesvirus infections." (PMID 29309427, 2018). "However, as responses against HSV-1 or KSHV de novo infections are not examined in these studies under similar IFI16 KO conditions, it is premature to conclude the role of IFI16 in the IFN-β response during the complex biology of various herpesvirus infections." (PMID 27764250, 2016). "However, the molecular mechanisms regulating these dynamic IFI16 behaviors during herpesvirus infection remain largely unknown." (PMID 27935834, 2016). "The DNA sensors IFI16, DNA-PK, RNF8, and RNF168 were shown to be degraded during herpesvirus infection." (PMID 33791247, 2021).
herpesvirus infection (continued). "During herpesvirus infection, the assembly and activation of NLRP3, AIM2 and IFI16 inflammasomes has been reported upon the detection of various viral PAMPs or DAMPs." (PMID 31798565, 2019). "Cytosolic receptors relevant to herpesvirus infection are the retinoic acid–inducible gene 1 (RIG-I), cGAS and Interferon Gamma Inducible Protein 16 (IFI16) sensors that detect dsRNA and dsDNA." (PMID 31234396, 2019). "Of these, IFI16 has received significant attention due to its role as a vDNA PRR in the induction of ISG expression and type-I IFN production during herpesvirus infection." (PMID 29309427, 2018). "More interestingly, we demonstrated that IFI16 is also necessary for initiating an early and robust interferon response to cytosolic DNA, HIV and herpes infections, and cGAMP stimulation in primary human macrophages." (PMID 28186168, 2017). "For instance, IFI16 was reported to mediate CD4+ T-cell programmed cell death upon HIV-1 infection and caspase-1-containing inflammasome formation upon herpesvirus infection." (PMID 27935834, 2016). "A concurrent study also shows that nuclear to cytoplasmic trafficking of IFI16 during herpesvirus infection is Ran-GTP dependent and mediated by the acetylation of IFI16 by the histone acetyl transferase p300." (PMID 27854239, 2016). "Our comprehensive studies for the first time demonstrate that acetylation of IFI16 after recognizing the viral genome occurs as a dynamic post-genome recognition event that is common to the IFI16-mediated innate responses of inflammasome induction and IFN-β production during herpesvirus infections." (PMID 26134128, 2015). "Thus, we hypothesize that the topology of replicating vDNA is important for the stable recruitment of IFI16 on to vDNA that leads to the induction of ISG expression and type-I IFN production during herpesvirus infection." (PMID 29309427, 2018).